GCG (glucagon)
Diseases named in the same sentence as GCG in open-access papers (continued):
Sharing a sentence is not in itself a finding about the gene and the disease.
type 1 diabetes (continued). "One study reported that individuals with type 1 diabetes had normal glucagon suppression after an intravenous compared with an oral glucose test, leading to the authors suggesting defective incretin mediated regulation of glucagon secretion in type 1 diabetes." (PMID 34405569, 2021). "The UVAPadova 2018 model is a maximal model that describes the relationship among glucose, insulin and glucagon only for patients with Type 1 diabetes." (PMID 34570804, 2021). "In recent years the role of altered alpha cell function and glucagon secretion in type 1 diabetes has attracted scientific attention." (PMID 34405569, 2021). "In another study, serum glucagon concentrations were compared between human patients with type-1 diabetes and matched healthy controls." (PMID 34941910, 2021). "Moreover, in individuals with type 1 diabetes exercise leads to a paradoxical increase in insulin concentrations believed to be caused by increased blood flow and absorption of subcutaneous deposits of insulin possibly contributing to the attenuated glucagon release." (PMID 34405569, 2021). "In our eyes, this paper highlights an important issue in type 1 diabetes – a derailed glucagon secretion, and hopefully inspires to further research into the glucagon conundrum of type 1 diabetes." (PMID 34405569, 2021). "Adults with type 1 diabetes and preserved C-peptide (>99 pmol/l after a mixed-meal tolerance test) have relative preservation of the glucagon response to hypoglycaemia." (PMID 32034440, 2020). "Sirt1 can greatly attenuate islet α cell hyperplasia in diabetic mice, reduce plasma glucagon concentration, significantly improve blood glucose control and thus treat type 1 diabetes." (PMID 32961025, 2020). "In general, athletes with type 1 diabetes perform training and competition with elevated circulating insulin levels and blunted glucagon responses that typically require a high rate of carbohydrate consumption in race events." (PMID 32533229, 2020). "The main purpose of these digital therapeutic devices has been to treat patients with type 1 diabetes with a device that injects insulin or glucagon subcutaneously based on continuous measurement of blood glucose." (PMID 32509974, 2020). "The Glucose-Insulin-Glucagon nonlinear model accurately describes how the body responds to exogenously supplied insulin and glucagon in patients affected by Type I diabetes." (PMID 30893335, 2019). "Nevertheless, growing evidence supports a concomitant implication of glucagon secreting α cells in type I diabetes progression." (PMID 31130919, 2019). "Type 1 diabetes (T1D) is an autoimmune disease characterised by the progressive depletion and destruction of pancreatic β-cells accompanied with impaired glucagon-producing α-cell function." (PMID 31336832, 2019). "On the other hand, a concomitant role of glucagon secreting pancreatic α cells in the pathogenesis of type I diabetes has been proposed." (PMID 31130919, 2019). "There were six statistically overrepresented pathways involved in glucose metabolism, including glucagon signaling pathway, insulin secretion, glycolysis/gluconeogenesis, aldosterone synthesis and secretion, type I diabetes mellitus, and propanoate metabolism." (PMID 30233306, 2018). "Abnormal glucagon secretion and functional alterations of the exocrine pancreas have been described in patients with type 1 diabetes (T1D), but their respective anatomical substrata have seldom been investigated." (PMID 29352311, 2018). "The reduction in hypoglycaemic burden in our study was almost identical to that in Russell and colleagues' study, which compared 5 day use of a bihormonal (insulin and glucagon) closed-loop system with usual pump therapy in adults with type 1 diabetes." (PMID 28094136, 2017). "Analysis of pancreata obtained from patients with long-term type 1 diabetes (n = 3) showed nearly complete loss of insulin positive cells, while some DPP6 and glucagon positive cells remained." (PMID 29123178, 2017).
type 1 diabetes (continued). "Successively, evidence has been reported of single cells in the pancreas of one healthy subject, containing both zymogen and insulin resembling granules, and of acinar cells in two individuals with type 1 diabetes with also glucagon granules." (PMID 28617859, 2017). "Although this would be compatible with the lack of an inhibitory effect during hypoglycaemia (when insulin secretion is halted), this cannot be the only mechanism, as GLP-1 strongly inhibits glucagon secretion in individuals with long-standing type 1 diabetes." (PMID 28551699, 2017). "The high levels of glucagon in type 1 diabetes and the low levels of insulin are probably an important cause for the elevated levels of glutaminase in this disease." (PMID 27490892, 2016). "Type III diabetes differs from type I diabetes as the damage of pancreatic islets is not limited to insulin secreting beta cells but is more diffused as it also affects glucagon and pancreatic polypeptide secreting alpha and PP cells." (PMID 25892991, 2015). "A definitive comparison in early Type 1 diabetes shows that C-peptide at 90 min in the mixed-meal tolerance test is more reproducible than post-glucagon C-peptide measurement and better tolerated." (PMID 23413806, 2013). "Human isolated islets from donors with type 1 diabetes do not secrete glucagon in response to low glucose, but treatment of these with a somatostatin receptor antagonist causes an increase in glucagon secretion." (PMID 40473678, 2025). "Tirzepatide was recently shown to reduce elevated fasting plasma glucagon in type 2 diabetes, but tirzepatide’s direct effect on alpha cells particularly in the context of type 1 diabetes remains unclear." (PMID 40374968, 2025). "Based on the results presented herein, we propose that the increased number of alpha cells connected per delta cell in type 1 diabetes could be an additional contributing factor to the impaired glucagon secretion in type 1 diabetes." (PMID 40473678, 2025). "However, few studies have evaluated insulin secretion and glucagon or cortisol levels in relation to NH in patients with insulin-dependent diabetes by using CGM." (PMID 40932945, 2025). "In type 1 diabetes, the counterregulatory glucagon response to low plasma glucose is impaired." (PMID 40374968, 2025). "We next investigated whether the alpha cells retain capacity to secrete glucagon in response to l-arginine following long-term cytokine exposure, as seen in type 1 diabetes." (PMID 40374968, 2025). "In type 1 diabetes, dysregulated glucagon secretion may exacerbate hyperglycaemia and contribute to metabolic excursions." (PMID 40629004, 2025). "PC1/3 and glucagon co-localisation was also increased in donors with type 1 diabetes." (PMID 39404844, 2024). "Looking forward, GABA may have unique and previously underappreciated therapeutic benefits in TID to increase β-cell content, reduce excess glucagon and curtail the inflammatory T-cell dysfunction of type 1 diabetes." (PMID 39619323, 2024). "In our study, adrenaline stimulated glucagon secretion in individuals with type 1 diabetes." (PMID 38427076, 2024). "The underlying mechanism may be related to GLP-2-dependent activation, where low insulin and high glucagon formed in type 1 diabetes promote GLP-2 secretion in the intestine, increasing GLUT-2 abundance in the BBM." (PMID 38333863, 2024). "Additional analyses of amidated GLP-1 in alpha cells and co-expression of insulin and glucagon are needed to support the hypothesis that alpha cells adapt in type 1 diabetes by acquiring beta cell identity and produce GLP-1 in islets." (PMID 39404844, 2024). "Previously, glucagon infusion has been shown to acutely increase glomerular filtration rate, renal blood flow, and renal excretion of electrolytes in dogs and sheep, in healthy human subjects, and in patients with type 1 diabetes." (PMID 39265079, 2024).
type 1 diabetes (continued). "In type 1 diabetes it has generally been assumed that the profound defect in alpha cell glucagon secretion is a consequence of autoimmune beta cell destruction, that is, that the loss of a paracrine signal or other beta cell-secreted factor is responsible for this defect." (PMID 38010533, 2024). "Increased urinary excretion of β2-microglobulin, a sign of renal damage, was demonstrated in healthy men when glucagon plasma concentrations were increased by infusion, corresponding to pathophysiological levels seen in patients with dysregulated type 1 diabetes mellitus." (PMID 39265079, 2024). "Defective α-cells and a reduced number of α-cells in type 1 diabetes alter glucagon responses." (PMID 38094502, 2023). "Consequently, insulin production decreases, and hyperactive alpha cells increase glucagon secretion in Type 1 Diabetes Mellitus (T1DM) patients." (PMID 38149165, 2023). "Interestingly, we only reported this positive association in the type 1 diabetes donors by microarray, but identified a strong positive correlation between islet RAGE and glucagon protein levels in all donor groups by confocal microscopy." (PMID 37558746, 2023). "The use of glucagon (any type) remains low, approximately 1/10 of persons with type 1 diabetes." (PMID 36550552, 2022). "The use of glucagon has always been ten fold greater in countries where new ready-to-use glucagons became available than in the other countries (population 108,000,000 vs 28,100,000, 480,291 vs 182,018 persons with type 1 diabetes)." (PMID 36550552, 2022). "The aims of this study were to evaluate the use of glucagon in persons with type 1 diabetes in several countries, and to investigate if the availability of new ready-to-use glucagons (Baqsimi, Gvoke, Zegalogue, years 2019 to 2021) has expanded the overall use of glucagon." (PMID 36550552, 2022). "Although reasons behind this remain speculative, previous studies have shown alterations also in glucagon-producing alpha cells in preclinical type 1 diabetes." (PMID 36171903, 2022). "However, especially within recent years the role of altered alpha cell function and glucagon secretion in type 1 diabetes has attracted considerable interest." (PMID 34405569, 2021). "It has previously been reported that glucagon responses to specific oral amino acid such as alanine, a mixture or intravenous administered alanine are preserved in type 1 diabetes." (PMID 34405569, 2021). "The regulation of glucagon secretion is complex, and different factors have been proposed to explain the blunted glucagon response to hypoglycaemia in type 1 diabetes, but the precise mechanism remains unclear." (PMID 33855225, 2021). "Interestingly, glucagon agonism (low-dose glucagon) is likely to be applied together with insulin in the dual pump systems development for type 1 diabetes therapy." (PMID 31284506, 2019). "Supporting these findings, a significant correlation between the parameters of hepatic lysosomal volume density and plasma glucagon was observed in rats with type 1 diabetes induced by streptozotocin, and insulin intervention in these rats led to suppression of glucose and glucagon levels." (PMID 31156426, 2019). "Similarly, acinar cells with also glucagon granules have been described in two individuals with type 1 diabetes." (PMID 28617859, 2017). "Therefore, in Type 1 diabetes, even physiological levels of AVP can cause a profound increase in blood glucose by stimulating glucagon secretion resulting in increased production of glucose by the liver." (PMID 25853137, 2015). "Inhibition of glucagon secretion may be involved in the efficacy of DPP-4 inhibitors for insulin-treated patients and inhibition of glucagon secretion as a GLP-1 receptor agonist may be important in type 1 diabetes." (PMID 26124906, 2015). "Type 1 diabetes (T1D) is characterized by the autoimmune destruction of most insulin-producing β cells, along with dysregulated glucagon secretion from pancreatic α cells." (PMID 41026524, 2025).
type 1 diabetes (continued). "To perform the converse analyses, we used generalized linear modelling (GLM) to see if islet GCG expression could be predicted in donors with type 1 diabetes using RAGE ligands and downstream signaling pathways for RAGE, instead of using the expression of AGER itself." (PMID 37558746, 2023). "In individuals with type 1 diabetes mellitus (T1DM), the mentioned hormonal balance, especially between insulin and glucagon, is disturbed." (PMID 36339413, 2022). "The physiological glucagon response to hypoglycaemia is often impaired in type 1 diabetes; therefore, addition of glucagon to a closed-loop system confers additional protection from hypoglycaemia and may allow more aggressive insulin delivery to achieve improved glucose control." (PMID 33550442, 2021). "As previously reported individuals with type 1 diabetes continuously secrete plasma glucagon after 14 hours of insulin withdrawal despite mean plasma‐glucose of around 20 mmol/L; and following intravenous insulin infusion glucagon concentrations are suppressed." (PMID 34405569, 2021). "In addition to the inability to lower insulin secretion into the portal circulation at exercise onset, glucagon fails to rise normally during prolonged exercise in type 1 diabetes, predisposing athletes to developing hypoglycaemia during some activities." (PMID 32533229, 2020). "This is exemplified by the findings of attenuated glucose production in response to exogenous glucagon after one week of low carbohydrate diet (LCD) compared to the response after a week of high carbohydrate diet (HCD) in patients with insulin pump-treated type 1 diabetes." (PMID 31284506, 2019). "Importantly, and as well as providing insights into the aetiopathology of T2D, changes in the normal release of glucagon may also have consequences for glycemic control in Type 1 diabetes (T1D)." (PMID 27390586, 2016). "In human pancreata, the abundance of α-cells compared to β-cells could lead to a functional excess glucagon secretion compared to insulin secretion and ultimately contributes to early clinical presentation in human type 1 diabetes, as advanced by Dr. Roger Unger and others." (PMID 26057531, 2015). "In addition, increased glucagon response to a mixed-meal stimulus has been noted previously in type 1 diabetes, suggestive that the α-cell secretory reserve may be unaffected by the progression of the autoimmune process." (PMID 24858952, 2014). "GLP-1 analogues, in addition to their insulin-tropic action, have beneficial effects in protecting pancreatic β-cell function, in suppressing glucagon secretion and in delaying gastric emptying, all characteristics which could be beneficial for the management of type 1 diabetes." (PMID 23806096, 2013). "In the near future, this model could also be implemented to simulate and/or predict calcium signals and glucagon release by pancreatic -cells in pathological situations such as type 1 diabetes, which is characterized by a lack or very low concentrations of insulin and elevated glucose levels." (PMID 22412861, 2012). "We further showed that the percentage of glucagon and PC1/3 double-positive cells is also elevated in islets from donors with recent-onset type 1 diabetes." (PMID 39404844, 2024). "We utilized random forest ensemble machine learning to generate a model to explain the expression of GCG using AGER and its correlated genes in islets from donors with type 1 diabetes." (PMID 37558746, 2023). "We found that islets from type 1 diabetes donors had differential expression of the RAGE gene (AGER) and its correlated genes, based on glucagon expression." (PMID 37558746, 2023). "The relationship between glucagon and RAGE was of interest in the islets of adolescent donors with type 1 diabetes as they were more recently diagnosed and had shorter disease duration." (PMID 37558746, 2023).
type 1 diabetes (continued). "Interestingly, we found that in type 1 diabetes donors with an inverse relationship between RAGE and GCG (hereby, T1D-adolescents), there was increased α cell RELA (vs. remaining type 1 diabetes donors)." (PMID 37558746, 2023). "However, this was necessary to first establish that our finding of a relationship between liver glycogen concentrations and glucagon secretion in the dog translates to man, after which it will be important to determine whether this relationship remains intact in patients with type 1 diabetes." (PMID 37166980, 2023). "This may happen because the secretion of glucagon and other hormones during exercise increases glucose production via glycogen breakdown in the liver to a rate much higher than the impaired rate at which the exercising muscles absorb glucose in some people with Type 1 Diabetes." (PMID 32155149, 2020). "The plasma glucagon concentration significantly increased throughout the adrenaline infusion in participants with type 1 diabetes (p=0.016) but not in the control group (p=0.067)." (PMID 38427076, 2024). "A dasiglucagon dose range of 10 to 70 μg/h was chosen for the trial based on clinical experience from the off-label use of glucagon in CHI patients and supportive data from a pharmacokinetic/pharmacodynamic model developed for a pediatric population (>25 kg) with type 1 diabetes (unpublished)." (PMID 37930757, 2024). "People with type 1 diabetes often have an absent glucagon response, making them heavily reliant on the epinephrine response to increase glucose levels." (PMID 37887414, 2023). "This period of elevated RAGE activation and excessive glucagon suppression may reflect the inverse relationship between glucagon and RAGE seen in the adolescent donors with type 1 diabetes." (PMID 37558746, 2023). "To establish cellular colocalization of GCG and RAGE, we performed line scan analysis where we found that GCG and RAGE were co-expressed in comparable domains of the α cells in islets from donors with type 1 diabetes." (PMID 37558746, 2023). "The optimized assay results were applied for measurement of glucagon turnover in subjects with and without type 1 diabetes infused with isotopically labeled glucagon tracers." (PMID 35590248, 2022). "The optimized targeted assay was then applied to measure glucagon turnover in study participants with and without type 1 diabetes." (PMID 35590248, 2022). "Almost all people with type 1 diabetes by around 5 years disease duration do not appear able to secrete glucagon in response to hypoglycaemia, while by 10 years disease duration the majority also have a suppressed autonomic response." (PMID 36251572, 2022). "We have demonstrated successful application of the isotope dilution technique to estimate glucagon turnover directly in vivo in humans with and without type 1 diabetes." (PMID 35590248, 2022). "We applied the optimized assay for calculation and estimation of glucagon kinetics in plasma with estimation of systemic glucagon turnover in participants with and without type 1 diabetes." (PMID 35590248, 2022). "Unlike epinephrine, glucagon is a less reliable marker of counterregulatory response impairment, especially in people with type 1 diabetes, and highly variable results are reported in animal HAAF models." (PMID 36676967, 2022). "Participants with or without type 1 diabetes were infused with heavy tracers of glucagon and arterialized venous samples were drawn periodically for measurements of 13C15N glucagon." (PMID 35590248, 2022). "In conclusion, these studies indicate that the mechanisms behind the absent glucagon secretion in type 1 diabetes appear to reside within the islets of Langerhans." (PMID 34405569, 2021). "Supporting this concept fasting concentration of glucagon have been found in some but not in all studies to be elevated in individuals with type 1 diabetes compared with nondiabetic individuals." (PMID 34405569, 2021).